VEGFB (vascular endothelial growth factor B)
Diseases named in the same sentence as VEGFB in open-access papers (continued):
Sharing a sentence is not in itself a finding about the gene and the disease.
injury (1 paper, 2019). Damage inflicted on the body as the direct or indirect result of an external force, with or without disruption of structural continuity. "Next, we determined the mechanism through which circAnks1a mediates the transcriptional regulation of VEGFB induced by nerve injury." (PMID 31511520, 2019). "Taken together, our findings indicated that circAnks1a facilitated the nuclear translocation and promoter binding of YBX1, thereby inducing VEGFB upregulation and neuropathic pain induced by nerve injury." (PMID 31511520, 2019). "Taken together, the present study for the first time demonstrated that enhanced interaction between circAnks1a and YBX1 can facilitate YBX1 nuclear translocation and its binding to the Vegfb promoter region and thereby lead to VEGFB upregulation induced by nerve injury." (PMID 31511520, 2019). "We further identified VEGFB as the target protein whose expression in the dorsal horn was meticulously regulated, at the transcriptional and translational levels, by circAnks1a, thus contributing to the central sensitization and the pain behavior induced by nerve injury." (PMID 31511520, 2019). "Considering our finding that circAnks1a siRNA completely inhibited the upregulation of VEGFB protein induced by nerve injury, another YBX1-independent pathway might exist through which circAnks1a regulates the expression of VEGFB in the setting of nerve injury." (PMID 31511520, 2019).
insomnia (1 paper, 2026). A sleep disorder characterized by difficulty in falling asleep and/or remaining asleep. "Among them, S100A3 showed consistent discriminatory performance across the training cohort, the independent sleep deprivation cohort, and the insomnia cohort, whereas VEGFB exhibited notable diagnostic potential, particularly in insomnia." (PMID 42216239, 2026).
kidney cancer (1 paper, 2022). Primary or metastatic malignant neoplasm involving the kidney. "Bulk RNA-seq datasets from 16 BHD-associated kidney cancers and 5 normal kidneys further showed that the expression levels of MET (p < 0.001) and vascular endothelial growth factor B (VEGFB) (p < 0.001) in BHD-associated kidney cancers were statistically higher than those in normal kidneys." (PMID 35874919, 2022).
lung diseases (1 paper, 2011). "We report here for the first time changes in PlGF and VEGFB expression in the lung in response to hypoxia in vivo mimicking that found in lung diseases." (PMID 21266048, 2011).
lung fibrosis (1 paper, 2023). "Based on the cluster analysis, we believe anti-VEGFB antibodies and anti-TRIM21/Ro52 antibodies should be further investigated in the context of digital ulcers and lung fibrosis and/or PAH in SSc patients." (PMID 36982700, 2023).
migraine (1 paper, 2024). "Our results showed VEGFB was downregulated in bulk dACC tissue in chronic pain, indicating VEGFB may represent a protective angiogenic factor outside of migraine, and in a general chronic pain context." (PMID 38826319, 2024).
Miscarriage (1 paper, 2022). A pregnancy that ends at a stage in which the fetus is incapable of surviving on its own, defined as the spontaneous loss of a fetus before the 22th week of pregnancy. "Likewise, in present study VEGFB expression was lower in AUB females with previous history of miscarriages compared to AUB females with no history of miscarriages." (PMID 36564776, 2022). "AUB women with miscarriage history showed upregulation in MMP2, TGFB3 (P < 0.05), and downregulation in MMP9 and VEGFB (P < 0.05) expression compared to AUB group with no miscarriage history." (PMID 36564776, 2022).
myxoid liposarcoma (1 paper, 2016). A liposarcoma characterized by the presence of round non-lipogenic primitive mesenchymal cells and small signet ring lipoblasts within a myxoid stoma with a branching vascular pattern. "Similarly, pharmacologic inhibition of eIF4E by 4EGI-1 decreased the expression of VEGFR1, VEGFR3, VEGFA, and VEGFB in myxoid liposarcoma cell lines." (PMID 27822137, 2016). "Similar to our finding that FUS-CHOP promotes angiogenesis, we also demonstrated that eIF4E promotes the production of angiogenic factors in myxoid liposarcoma cell lines, as eIF4E siRNA knockdown significantly reduced the expression of VEGFA, VEGFB, and VEGFR3." (PMID 27822137, 2016).
pituitary tumor (1 paper, 2022). A benign or malignant neoplasm affecting the pituitary gland. "Pituitary tumors also expressed significantly higher levels of angiogenesis growth factors, including VEGFA (4.2-fold), VEGFB (2.2), VEGFC (19.3), PGF (13.4), ANGPT2 (9.2), PDGFA (2.7), PDGFB (10.5) and TGFB1 (3.8) compared to normal pituitary tissue." (PMID 35600354, 2022). "Compared with normal pituitary tissue, genes with the highest to lowest expression levels in pituitary tumor tissue were VEGFC (19.3-fold, p<0.0001), PGF (13.4-fold, p<0.0001), VEGFA (4.2-fold, p<0.0001) and VEGFB (2.2-fold, p=0.002)." (PMID 35600354, 2022). "Furthermore, we identified PGF and VEGFC, but not VEGFA or VEGFB, as the major angiogenic growth factors regulating angiogenesis in human pituitary tumors." (PMID 35600354, 2022). "Angiogenesis in pituitary tumors is regulated mainly by PGF and VEGFC, not VEGFA and VEGFB." (PMID 35600354, 2022).
polyp (1 paper, 2024). A usually exophytic mass attached to the underlying tissue by a broad base or a thin stalk. "Specifically, compared with normal tissues, monocytes, pDCs and epithelial subsets had increased expression levels of VEGFA and/or VEGFB, while endothelial cells had increased expression levels of VEGF receptors FLT1 and KDR in three polyp subtypes." (PMID 38264936, 2024).
sarcoidosis (1 paper, 2025). Sarcoidosis is a multisystemic disorder of unknown cause characterized by the formation of immune granulomas in involved organs. "Furthermore, LTBR showed significant associations in the sarcoidosis UK Biobank cohort using the significant-variant strategy, while VEGFB and ANXA11 showed associations using the same-variant strategy." (PMID 39824903, 2025). "Consequently, we cannot rule out the possibility that RA might enhance the causal effect of VEGFB on sarcoidosis." (PMID 39824903, 2025). "Lastly, to mitigate bias from horizontal pleiotropy, we utilized “Phenoscanner” and “LDlink” to identify significant associations (P < 5 × 10–8) between rs660442 and rs2278236—cis-pQTLs for VEGFB and ANGPTL4, respectively—and phenotypes potentially linked to sarcoidosis." (PMID 39824903, 2025). "Additionally, three out of the four proteins preliminarily identified for sarcoidosis—VEGFB (coloc.abf-PPH4 = 0.907), LTBR (coloc.abf-PPH4 = 0.947), and ANGPTL4 (coloc.abf-PPH4 = 0.957)—received robust support by genetic colocalization analysis (PPH4 > 0.8) under standard priors and window (± 1 Mb)." (PMID 39824903, 2025).
systemic lupus erythematosus (1 paper, 2024). An autoimmune multi-organ disease typically associated with vasculopathy and autoantibody production. "As systemic lupus erythematosus (SLE) is a severe autoimmune inflammatory disease and abnormal activation of CD4+ T cells plays predominant roles in the pathogenesis of SLE, we detected the expression of VEGFB and FLT1 in CD4+ T cells from patients with SLE." (PMID 39145452, 2024).
tendinopathy (1 paper, 2024). "The current study showed that all studied VEGFB gene SNPs were associated with the efficacy of lateral elbow tendinopathy treatment with platelet-rich plasma." (PMID 39684876, 2024). "The association of the VEGFB with the treatment of tendinopathy seems to be mainly related to the influence of this protein on pathological angiogenesis and muscle development." (PMID 39684876, 2024). "Therefore, reduced VEGFB activity, which translates into muscle growth, may lower the risk of developing tendinopathy." (PMID 39684876, 2024). "Lower activity of the VEGFB gene can also be beneficial in treating tendinopathy since its inhibition reduces pathological angiogenesis." (PMID 39684876, 2024). "The determination of the exact VEGFB role in tendinopathy treatment requires more detailed research." (PMID 39684876, 2024). "Due to the lack of data on the impact of VEGFB gene SNPs on tendinopathy or PRP therapy, the polymorphisms for the study were selected mainly based on their appropriate frequency in the studied population." (PMID 39684876, 2024).
Type 1 diabetes (1 paper, 2018). "Our own studies show that in an STZ model of Type 1 diabetes in rats, there is a robust decrease in VEGFB." (PMID 29732375, 2018).
tumor (161 papers, 2003 to 2025). "Conversely, FOLFOX-Bev impairs the functionality of tumor-associated macrophages, plasma cells, and cancer-associated fibroblasts, leading to a decrease in VEGFB-mediated angiogenesis." (PMID 37576892, 2023). "The response to chemotherapy is associated with tumor angiogenesis, and miR-484 has a potential to improve chemosensitivity through the modulation of tumor angiogenesis, by directly targeting VEGFB and KDR (formerly called VEGFR2)." (PMID 25295252, 2014). "Several elevated ligand-receptor pairs in CML were related to cancer development, such as ADRB2_VEGFB, which was involved in tumor angiogenesis, and BTLA_TNFRSF14, which was reported in immune regulation." (PMID 40612663, 2025). "A recent report showed that VEGFB promoted trans-endothelial delivery of LCFAs to tumor cells through mTORC1 signaling, and loss of endothelial mTORC1 reduced LCFA in tumor cells and T cell in lung metastatic TME, leading to metastasis inhibition." (PMID 39567756, 2025). "Increased P2X7R expression was found to significantly correlate with the expression levels of 5 ‘tumour-promoting’ mediators – VEGFB, IL-4, MMP-9, PCNA and IL-8." (PMID 41034696, 2025). "Analysis based on tumour grade using the UALCAN portal revealed specific expression patterns such as increased VEGFA expression in grade 2 and grade 3 tumours, elevated VEGFB expression in grade 3 tumours and high KDR expression in grade 4 tumours." (PMID 38426619, 2024). "In agreement with the general tumour‐promoting profile of VEGFB, its upregulation in CRC tissues and regulatory functions in CRC progression were also displayed in this study." (PMID 38775031, 2024). "Various studies have reported that VEGFA and VEGFB expression is higher in malignant tissues than in normal oral mucosa, and they play a significant role in enhancing angiogenesis and tumour growth in OSCC." (PMID 38426619, 2024). "CXCR1 and PTGS2 genes had significantly higher expression in patients with N1 metastasis, whereas VEGFB expression was significantly higher in tumour samples with N3 metastasis." (PMID 38426619, 2024). "VEGFB facilitates tumor advancement by elevating plasminogen activators, which can lead to the metastasis of breast cancer." (PMID 37852616, 2023). "High expression of RAC1, RHOA, CDC42, and VEGFB were identified in metastatic subgroups, compared to primary tumor and normal lung epithelia clusters." (PMID 37202394, 2023). "In one study, exogenous histidine administration resulted in a decrease in the expression of tumor markers associated with glycolysis (GLUT1 and HK2), inflammation (STAT3), angiogenesis (VEGFB and VEGFC), and stem cells (CD133)." (PMID 37760495, 2023). "This process is regulated by modulation of the tumor vascular system induced by the VEGFB and VEGFR2 pathways and is involved in tumor angiogenesis." (PMID 36439168, 2022). "Through immune checkpoint gene expression analysis, the expression of HM13 was found to exhibit a significant correlation with several tumor inhibitory genes, especially VEGFB, LAG3, CD274, and TGFB1." (PMID 36046831, 2022). "Consistent with the in vitro gene expression data for VEGFA and VEGFB showing induction after IL-21 treatment of Farage cells, in vivo we observed promotion of tumour angiogenesis." (PMID 32704112, 2020). "We also present data showing that HRAS capacity to regulate tumor growth/dissemination is dependent on vascular endothelial growth factor B (VEGF-B) secretion." (PMID 32927904, 2020). "Probably, resveratrol plays a dual role in PC: it suppresses tumor growth via Bax stimulation, but also stimulates tumor growth via vascular endothelial growth factor B (VEGF-B) activation, with the first effect being dominant." (PMID 32585831, 2020). "In fact, although VEGFB overexpression predicts for increased distant metastasis and shorter OS in advanced cancers, it was also shown to delay tumor growth in a mouse model of pancreatic neuroendocrine tumorigenesis." (PMID 31552188, 2019).
tumor (continued). "Nevertheless, we propose the VEGF ligands/receptors interplay (unbalanced in AFP-high tumours due to VEGFB/PGF overexpression) as a rationale for the enhanced activation of the VEGF pathway and thus the efficacy of ramucirumab in AFP-high HCC3." (PMID 31285588, 2019). "In addition, the levels of CXCL1, CXCL8, VEGFA, and VEGFB related to monocyte recruitment and angiogenesis were higher in patients with advanced stages than in those with tumor stage 1." (PMID 40860188, 2025). "The secreted factors induced by BCAM in tumor cells, and indirectly through the tumor cell secretome in mesothelial cells, likely cooperate to promote angiogenesis, e.g. through VEGFB produced by tumor cells, CXCXL8 expressed by mesothelial cells and FGF2 secreted by both cell types." (PMID 40082910, 2025). "Furthermore, both ADRB2 and VEGFB have been mentioned in studies related to cardiovascular disease, vessel growth, and tumor angiogenesis." (PMID 40175432, 2025). "Additionally, the role of angiogenic factors, such as vascular endothelial growth factor B (VEGFB), in modulating the tumor microenvironment and influencing immune checkpoint expression is an area of ongoing research." (PMID 40458414, 2025). "The risk score was positively correlated (r > 0.1) with VEGFA, VEGFB, and ICAM1, suggesting enhanced angiogenesis that may restrict immune infiltration and promote tumor progression." (PMID 41293172, 2025). "Importantly, elevated levels of VEGFB, PDGFRA, MAPK13, and HGF have been previously linked to poor prognosis and aggressive tumor behavior in HCC." (PMID 41002582, 2025). "VEGFB and KDR are often associated with angiogenesis‐mediated resistance because they stabilise the tumour microenvironment by ensuring an adequate supply of oxygen and other nutrients required for tumour growth, further adjusting the tumour microenvironment for optimum disease progression." (PMID 38426619, 2024). "Moreover, the expression of ADAM10 was reciprocally exclusive with some tumor immune checkpoint genes, such as VEGFB, LAG3, IL4, TNFRSF18, TNFRSF4, TNF receptor superfamily member 14 (TNFRSF14), CD27, CCL5, etc.." (PMID 39211038, 2024). "By profiling the immune modulators, we found that some suppressors, including B7‐H3, LAG3, VEGFB and Siglec‐15, are significantly upregulated in tumor tissues, which may contribute to the relatively suppressive immune microenvironment in SCCE." (PMID 33033616, 2020). "The role of VEGFB in tumor progression remains controversial." (PMID 31552188, 2019). "For expression of genes involved in vascular morphogenesis and maturation, it was reported that low VEGFB and high FLT1 in primary tumours and high ACVRL1 levels in liver metastases were associated with enhanced OS of CRC patients with liver metastases treated with bevacizumab plus chemotherapy." (PMID 29535825, 2018). "Interestingly, a study found that gain of VEGFB function in a cancer cell line with low VEGFB resulted in an increase in circulating tumor cells and metastases." (PMID 29732375, 2018). "Whether the observed VEGFB-dependent changes in tumor growth rate in the RIP1-Tag2 model are due to an altered supply or utilization of glucose warrants further analysis by a PET-based approach." (PMID 21124841, 2010). "Therefore, the specific pattern of APA modification on our predicted VEGFB might also be an applicable biomarker of different tumor types, validating the efficacy and accuracy of our prediction." (PMID 32626751, 2020). "Vascular endothelial growth factor-B could contribute to the maintenance of host–tumour responses." (PMID 12942123, 2003). "The VEGF protein family consists of VEGFA, VEGFB, VEGFC, VEGFD, and many others, some members of which are inducers of tumor lymphangiogenesis." (PMID 39866224, 2025).